CCNL2 (cyclin L2)
Description:
Regulatory component of the cyclin-L-CDK11 complex that regulates transcription and pre-mRNA splicing.
Synonyms: SB138; ania-6b; PCEE; HLA-ISO; CCNS; CCNM; HCLA-ISO
Tractability: PROTAC: ubiquitination databases record sites on it; its protein half-life has been measured.
Gene: Protein-coding gene on chromosome 1 (1,385,711 to 1,399,339, reverse strand). Ensembl gene ENSG00000221978.
Subcellular location: Nucleus speckle; Nucleus, nucleoplasm
Subcellular location (Human Protein Atlas): Nucleoplasm; Basal body; Cytosol; Vesicles
Gene Ontology:
Molecular function: cyclin-dependent protein serine/threonine kinase regulator activity; protein binding
Biological process: regulation of mRNA splicing, via spliceosome; regulation of RNA splicing; regulation of apoptotic process; regulation of cell cycle; regulation of centrosome cycle; regulation of transcription by RNA polymerase II
Cellular component: cyclin L-CDK11 complex; cyclin-dependent protein kinase holoenzyme complex; nuclear speck; nucleoplasm; nucleus
Genetic constraint (gnomAD): Loss-of-function variants: 28 observed, 57.75 expected, observed/expected ratio (o/e) 0.48, 90% interval 0.36 to 0.67. The upper end of that interval is the gene's LOEUF score, 0.67, which puts it in group 2 of 6, group 1 being the genes least tolerant of losing a copy. Missense variants: 711 observed, 726.13 expected, observed/expected ratio (o/e) 0.98, 90% interval 0.92 to 1.04. Synonymous variants: 342 observed, 296.6 expected, observed/expected ratio (o/e) 1.15, 90% interval 1.05 to 1.26.
Homologues: Orthologues: chimpanzee CCNL2 (99% identical), dog CCNL2 (92% identical), pig CCNL2 (90% identical), mouse Ccnl2 (89% identical), guinea pig CCNL2 (89% identical), rat Ccnl2 (89% identical), macaque CCNL2 (88% identical), rabbit CCNL2 (86% identical), tropical clawed frog ccnl2 (68% identical), Drosophila melanogaster CycT (18% identical), Caenorhabditis elegans cit-1.2 (18% identical), Caenorhabditis elegans cit-1.1 (15% identical), and 2 more. Paralogues in human: CCNL1 (60% identical), CCNT2 (23% identical), CCNT1 (21% identical), CCNK (19% identical), CCNQ (14% identical), CCNH (11% identical).
Diseases named in the same sentence as CCNL2 in open-access papers:
CCNL2 is named in the same sentence as 21 diseases in open-access papers, as found by Europe PMC text mining. Sharing a sentence is not in itself a finding about the gene and the disease. The quoted sentences say what the papers report.
hepatoma (3 papers, 2021 to 2023). "A previous study has demonstrated that CCNL2 was involved in pre-mRNA splicing and induced apoptosis of human hepatocellular carcinoma cells." (PMID 34201256, 2021). "CCNL2 was reported to promote apoptosis of human hepatoma cells in vitro." (PMID 36613552, 2022).
lung carcinoma (3 papers, 2021 to 2024). "The highest-ranked genes in both cohorts of primary lung cancers and LC-BrMs included CCNL2, DVL1, ATAD3A, AGRN, and ISG15, where mutation patterns were clustered for the patients." (PMID 39593114, 2024). "The parental gene CCNL2 encodes a cyclin family protein that can interact with a variety of proteins to induce cell cycle arrest and apoptosis in lung cancer and mouse embryonic cancer cells." (PMID 34381020, 2021). "CCNL2 overexpression is also known to induce apoptosis and cell cycle arrest of human lung cancer cells." (PMID 36613552, 2022).
breast carcinoma (2 papers, 2015 to 2020). "A recent preclinical study conducted in breast cancer cell lines and tissue arrays reported that CCNL2 mRNA transcript expression was lower in breast cancer than in normal breast tissue." (PMID 32290274, 2020). "Cyclin L2 transcript expression was also significantly lower in basal breast cancer than in normal breast." (PMID 25837326, 2015). "RNA expression levels of CDC2L1, CDC2L2, CCNL1, CCNL2, CSNK2A1, CSNK2A2, and CSNK2B genes in breast cancer subtypes were analyzed." (PMID 25837326, 2015).
prostate carcinoma (2 papers, 2022 to 2023). A carcinoma that arises from epithelial cells of the prostate gland. "Other studies identified the AC005154.6/hsa-miR-29c-3p/CCNL2 axis as a novel prognostic biomarker associated with immune infiltration in prostate cancer." (PMID 37238729, 2023). "In this study, we discovered that CCNL2 gene copy numbers were associated with the infiltration levels of most immune cells in prostate cancer and that CCNL2 expression had a notable correlation with CD8 + T cells." (PMID 36369040, 2022). "We identified the AC005154.6/CCNL2 axis as a risk factor that can promote the progression of prostate cancer by bioinformatics analysis and molecular experiments." (PMID 36369040, 2022). "The methylation level of CCNL2 was significantly decreased in tumor samples, possibly contributing to the upregulation of CCNL2 in prostate cancer." (PMID 36369040, 2022). "All the results indicated that prostate cancer proliferation and migration may be promoted by CCNL2." (PMID 36369040, 2022). "Moreover, a prognostic model was established based on the ceRNA network, and the AC005154.6/hsa-miR-29c-3p/CCNL2 axis provided guidance for the diagnosis, targeted therapy, and immunotherapy of prostate cancer." (PMID 36369040, 2022).
breast tumors (1 paper, 2020). "Low BRCA1 expression in cells along with BRCA1 inactivation in breast tumors is associated with reduced expression of CCNL2, DBF4B, and TRIM45." (PMID 32290274, 2020). "Given the functional implications of BRCA1 inactivation on the translation of ADAT2, CCNL2, DBF4B, and TRIM45, we wondered whether the levels of these proteins were correlated to BRCA1 status in breast tumors." (PMID 32290274, 2020).
dilated cardiomyopathy (1 paper, 2022). Cardiomyopathy which is characterized by dilation and contractile dysfunction of the left and right ventricles. "The GSEA results indicated that the upregulation of CCNL2 was associated with pathways such as salmonella infection, proteoglycans in cancer and dilated cardiomyopathy." (PMID 36369040, 2022).
embryonic carcinoma (1 paper, 2022). "Overexpression of CCNL2 has been reported to inhibit the proliferation and differentiation of mouse embryonic carcinoma P19 cells and induce them to undergo apoptosis." (PMID 35710353, 2022).
melanoma (1 paper, 2019). A malignant, usually aggressive tumor composed of atypical, neoplastic melanocytes. "We present data on CDK11, CCNL1 and CCNL2 mRNA expression in melanoma patients, including prognosis for survival." (PMID 30987032, 2019). "To understand CDK11 function in melanoma, we evaluated protein and RNA levels of CDK11, Cyclin L1 and Cyclin L2 in benign melanocytes and BRAF- as well as NRAS-mutant melanoma cell lines." (PMID 30987032, 2019). "It is not surprising that the genes CDK11A and CDK11B and CCNL2, which are all located on chromosome 1p, showed good correlation of expression at the mRNA level in melanoma patient tumor tissues." (PMID 30987032, 2019). "Gene mutation is not a major component of CDK11A, CDK11B, CCNL1 or CCNL2 function in melanoma." (PMID 30987032, 2019).
pancreatic cancer (1 paper, 2023). "In addition, inhibited exon skipping of METTL14 and enhanced exon skipping of Cyclin L2 caused by CLK1’s enhancing SRSF5 SRSF5250-Ser phosphorylation enhanced the N6-methyladenosine modification level and cancer aggressiveness in pancreatic cancer." (PMID 36977668, 2023).
systemic lupus erythematosus (1 paper, 2020). An autoimmune multi-organ disease typically associated with vasculopathy and autoantibody production. "The lncRNA encoded by splicing of the gene RP4-758J18.2 has previously been shown to play a role in the progression of systemic lupus erythematosus (SLE) through its interaction with CCNL2 gene." (PMID 32887511, 2020).
ventricular septal defect (1 paper, 2021). The presence of a defect (opening) in the septum that separates the two ventricles of the heart. "Zhuo et.al have revealed that Cyclin L2 expression was upregulated in ventricular septum tissue of ventricular septal defect (VSD) patients, and demonstrated that Cyclin L2 can regulate growth, differentiation, and apoptosis of P19 cells via inhibiting the WNT pathway." (PMID 33849617, 2021).
cancer (13 papers, 2009 to 2024). A tumor composed of atypical neoplastic, often pleomorphic cells that invade other tissues. "Moreover, CCNL2 is differentially expressed in multiple cancers and is tightly correlated with immune infiltration." (PMID 36369040, 2022). "Indeed, AC005154.6, hsa-miR-29c-3p and CCNL2 have all been explored for their possible roles in cancer." (PMID 36369040, 2022). "Cyclin L2 was reported to regulate cell cycle and proliferation in many types of cancers." (PMID 33849617, 2021). "Furthermore, functional enrichment analysis, mutation landscape analysis, immune infiltration analysis, drug sensitivity analysis, methylation analysis, pan-cancer analysis, and molecular experiments of CCNL2 were carried out to investigate the role of CCNL2 in tumorigenesis." (PMID 36369040, 2022). "SRSF5 is reported to promote cancer development and progression by regulating the splicing of multiple genes, including ETS1, METTL14, Mcl-1, Cyclin L2, and CCAR1." (PMID 38263157, 2024). "We assessed the correlation of CCNL2 expression and CD8 + T cell infiltration levels in 33 types of cancer." (PMID 36369040, 2022). "We focused on ADAT2, CCNL2, DBF4B, and TRIM45 mRNAs that played key roles in cancer biology to demonstrate that alteration of their translational efficiency occurred via a BRCA1-dependent mechanism in cultured cells and in patient tumors." (PMID 32290274, 2020).
tumor (5 papers, 2017 to 2022). "Aberrant METTL14 exon 10 exclusion enhances the N6-methyladenosine modification in PDAC cells which promotes tumor metastasis, while aberrant splicing of Cyclin L2 exon 6.3 promotes tumor proliferation." (PMID 36140826, 2022). "CCNL2 (Cyclin L2) is a member of the cyclin family, which was also reported to have tumor suppressor functions in HCC." (PMID 28038442, 2017). "Downregulation of CCNL2 suppressed tumor cell migration and colony formation." (PMID 36369040, 2022). "Therefore, positively controlling CCNL2 translation may represent a novel mechanism through which BRCA1 exerts its tumor suppressive activity." (PMID 32290274, 2020).
CCNL2 also shares sentences with these, for which no sentence is quoted: Fanconi anemia (1 paper); lung adenocarcinoma (1); metabolic disorders (1); neurological diseases (1); pulmonary hypertension (1); Salmonella Infections (1); Spastic paraplegia 7 (1); theileriasis (1).